SMS (spermine synthase)
Description:
Catalyzes the production of spermine from spermidine and decarboxylated S-adenosylmethionine (dcSAM).
Synonyms: SPMSY; SpS; MRSR; MRXSSR; SRS
Tractability: Small molecule: a structure with a bound ligand is known; it has a high-quality binding pocket; it belongs to a druggable protein family. PROTAC: ubiquitination databases record sites on it; its protein half-life has been measured; a small molecule that binds it is known.
Target class: Enzyme; Transferase
Gene: Protein-coding gene on chromosome X (21,940,709 to 21,994,837, forward strand). Ensembl gene ENSG00000102172.
Subcellular location (Human Protein Atlas): Nuclear bodies; Cytosol
Pathways (Reactome):
Metabolism: Metabolism of polyamines
Gene Ontology:
Molecular function: spermine synthase activity
Biological process: polyamine metabolic process; spermine biosynthetic process
Cellular component: extracellular exosome; cytosol
Gene-disease validity (ClinGen):
ClinGen rates the evidence that SMS causes each of these diseases.
syndromic X-linked intellectual disability Snyder type (X-linked): Definitive.
Homologues: Orthologues: macaque SMS (99% identical), rat Sms (97% identical), mouse Sms (96% identical), pig SMS (95% identical), dog SMS (94% identical), rat AABR07021734.1 (87% identical), tropical clawed frog sms (78% identical), rabbit SMS (74% identical), zebrafish sms (69% identical), Drosophila melanogaster Sms (44% identical). Paralogues in human: SRM (20% identical).
Diseases named in the same sentence as SMS in open-access papers:
SMS is named in the same sentence as 61 diseases in open-access papers, as found by Europe PMC text mining. Sharing a sentence is not in itself a finding about the gene and the disease. The quoted sentences say what the papers report.
Snyder-Robinson syndrome (19 papers, 2010 to 2025). "Gain-of-function mutations in the C-terminus of ODC have been connected to Bachmann-Bupp Syndrome (BABS; OMIM #619075) and loss-of-function mutations in spermine synthase are associated with Snyder-Robinson Syndrome (SRS)." (PMID 36848144, 2023). "As the first confirmed genetic disorder associated with the polyamine metabolic pathway, Snyder-Robinson syndrome (SRS) is caused by X-linked recessive loss-of-function mutations in spermine synthase (SMS)." (PMID 35801587, 2022). "Derangements in polyamine homeostasis are also associated with neurological maladies, where for example, mutations in spermine synthase and the ensuing changes in polyamine levels are the cause of Snyder-Robinson Syndrome." (PMID 33054763, 2020). "Loss of function mutations in the spermine synthase gene (SMS) have been reported to cause a rare X-linked intellectual disability known as Snyder-Robinson Syndrome (SRS)." (PMID 32838743, 2020). "Patients with Snyder-Robinson Syndrome (SRS) exhibit deficient Spermine Synthase (SMS) gene expression, which causes neurodevelopmental defects and osteoporosis, often leading to extremely fragile bones." (PMID 31659216, 2019). "A protective effect of SMS activity on FGR is supported by the phenotype of SMS deficiency in humans (Snyder-Robinson syndrome), where the average birth weight (BW) of babies born at term was ~500 g less than the population average of 3,300 g." (PMID 29997303, 2018). "First described in 1969, Snyder-Robinson Syndrome (SRS) is an X-linked intellectual disability syndrome resulting from mutation of the spermine synthase (SMS) gene, located at chromosome Xp22.11." (PMID 30544565, 2018). "Loss-of-function mutations of the spermine synthase gene (SMS) result in Snyder-Robinson Syndrome (SRS), a recessive X-linked syndrome characterized by intellectual disability, osteoporosis, hypotonia, speech abnormalities, kyphoscoliosis, and seizures." (PMID 30544565, 2018). "Mutations in spermine synthase lead to Snyder-Robinson syndrome, a form of intellectual disability syndrome." (PMID 29097652, 2017). "Missense mutations in spermine synthase (SpmSyn) protein have been shown to cause the Snyder-Robinson syndrome (SRS)." (PMID 26761001, 2016). "Mutations of SMS, the gene encoding spermine synthase, cause Snyder-Robinson syndrome (SRS), an X-linked disorder first reported in 1969." (PMID 25888122, 2015). "This work focuses on the missense mutation G56S causing malfunctioning of the enzyme spermine synthase and resulting in the Snyder-Robinson Syndrome." (PMID 25340632, 2014). "Here, we report a study focusing on a missense mutation G56S occurring in the vicinity to the homo-dimer interface of the human enzyme spermine synthase (SMS) and causing a rare mental retardation disorder, the Snyder Robinson Syndrome (SRS)." (PMID 25340632, 2014). "Loss of SPM due to mutations in spermine synthase (SMS) is known to cause Snyder-Robinson syndrome (SRS), an-X-linked intellectual disability that includes other symptoms, in particular hypotonia, skeletal defects, movement disorders, speech/vision impairment, seizure and cerebellar dysfunction." (PMID 34068137, 2021). "Till date, 11 hemizygous variants in SMS gene causing Snyder-Robinson syndrome so far reported." (PMID 32838743, 2020). "Indeed, several rare mutations in SMS, resulting in altered splicing or enzymatic activity, are responsible for Snyder-Robinson syndrome, a form of X-linked mental retardation which manifests with both intellectual and physical symptoms including alterations in brain morphology." (PMID 21152090, 2010). "Monogenic LOF mutations in spermine synthase (SMS) causes an X-linked intellectual disability disorder, Snyder-Robinson syndrome, due to increased polyamine synthesis suggesting a possible dose effect of polyamine production on neurodevelopment." (PMID 40894642, 2025).
Snyder-Robinson syndrome (continued). "Snyder-Robinson syndrome (SRS) is the first known genetic disorder of the polyamine pathway, caused by X-linked recessive loss-of-function mutations in spermine synthase." (PMID 35801587, 2022). "Snyder-Robinson syndrome (OMIM #309583, SRS) is caused by loss of function mutations in the spermine synthase gene (OMIM #300015, SMS)." (PMID 32838743, 2020). "Loss-of-function mutations in spermine synthase (SMS), a polyamine biosynthesis enzyme, cause Snyder-Robinson syndrome (SRS), an X-linked intellectual disability syndrome; however, little is known about the neuropathogenesis of the disease." (PMID 29097652, 2017). "Snyder-Robinson Syndrome (SRS) is a rare mental retardation disorder which is caused by the malfunctioning of an enzyme, the spermine synthase (SMS), which functions as a homo-dimer." (PMID 25340632, 2014). "In humans, this deficiency results in the Snyder-Robinson syndrome (SRS), which is a disease caused by the X-linked SMS gene defects." (PMID 23468611, 2013). "In this study we examine the human spermine synthase (HsSMS), for which currently there are no nsSNPs, while rare disease mutations are known to cause Snyder-Robinson syndrome." (PMID 23468611, 2013). "The common neurological phenotypes resulting from mutations in SMS, ODC1, and TSC and their association with dysregulated polyamine metabolism suggest that the knowledge obtained from the current studies might serve to benefit a patient population beyond those with Snyder-Robinson Syndrome." (PMID 30544565, 2018).
Intellectual disability (8 papers, 2016 to 2025). "Examples include SUMF1, KDM5B and MXRA5 (Known-ASD genes), PRODH2 and KCTD21 (implicated in schizophrenia), as well as USP9X and SMS (implicated in intellectual disability)." (PMID 28720891, 2017). "Examples include PRODH2 and KCTD21 (implicated in schizophrenia), USP9X and SMS (implicated in intellectual disability), TRIM9 and KDM5B (known-ASD genes), and others such as AGL and MOGS (candidate genes involved in energy metabolism and immune responses, respectively)." (PMID 28720891, 2017). "Mutations in spermine synthase lead to the Gyro phenotype in mouse and cause Snyder–Robinson syndrome in humans, an X-linked mental retardation condition characterized by intellectual disability, hypotonia, facial asymmetry and unsteady gait." (PMID 27215328, 2016). "SMS deficiency in humans causes Snyder‐Robinson syndrome (SRS), an X‐linked intellectual disability, and in Drosophila melanogaster, it leads to survival deficits and synaptic degeneration due to increased spermidine catabolism." (PMID 40081835, 2025). "The first identified polyamine pathway-related genetic disorder Snyder–Robinson Syndrome (SRS) is caused by mutations in spermine synthase (SMS), characterized by developmental delay, muscle/bone abnormalities, and intellectual disability." (PMID 38740758, 2024). "Phenotypic traits further support a correlation between MyoVa and SMS, since patients harboring loss-of-function mutations in SMS or MYO5A genes share some neurological symptoms, including intellectual disability, seizures, and hypotonia." (PMID 30733278, 2019).
colorectal cancer (7 papers, 2019 to 2023). A primary or metastatic malignant neoplasm that affects the colon or rectum. "The overexpression of SMS can facilitate colorectal cancer cell growth, while the inhibition of SMS expression may be associated with TGF-β-induced growth inhibition in hepatoma cells." (PMID 35804447, 2022). "Here, the authors show that a polyamine biosynthetic enzyme, spermine synthase, is overexpressed in colorectal cancers and cooperates with MYC to prevent cancer cell apoptosis by repression of proapoptotic protein, Bim." (PMID 32591507, 2020). "A recent study had demonstrated that downregulation of both SMS and MYC synergistically induces apoptin Bim expression in colorectal cancer cells, indicating that combined inhibition of SMS and MYC signaling may be an effective therapy for colorectal cancer." (PMID 33292222, 2020). "SMS, a polyamine biosynthetic enzyme, is overexpressed in patients with colorectal cancer and collaborates with MYC to promote colorectal cancer cell survival." (PMID 33869278, 2021). "In addition, recent studies have shown that SMS and MYC can synergistically inhibit the expression of pro-apoptotic protein Bim to maintain the growth of colorectal cancer cells." (PMID 37709932, 2023). "These analyses reveal the unknown effect of SMOX, SMS, and SRM genes in colorectal cancer." (PMID 31417867, 2019). "SMS, a polyamine biosynthetic enzyme with no reported role in NSCLC thus far, is overexpressed in colorectal cancer and its disruption leads to accumulation of spermidine, which induces the expression of proapoptotic protein Bim." (PMID 35676822, 2023).
breast cancer (5 papers, 2015 to 2024). A primary or metastatic malignant neoplasm involving the breast. "The overall survival rates of breast cancer patients based on the expression of these three genes (SMS, PAFAH1B2 and PDK3) were analyzed by UCSC Xena (data retrieved on November 24, 2020)." (PMID 33494814, 2021). "We then tested the degradation of RBM39 (nuclear) and SMS (cytoplasmic) N-terminally tagged with iTAG (DCD23) in CT26 and AT3 (murine mammary cancer lines)." (PMID 37360684, 2023). "Paclitaxel treatment elevated intracellular levels of ornithine and total polyamine (including putrescine, spermidine, and spermine), and increased expression of ODC1 and SRM (but not SMS) in breast cancer cell lines." (PMID 39058337, 2024). "However, the specific biological functions of SMS, PAFAH1B2, or PDK3 need to be further investigated in breast cancer." (PMID 33494814, 2021).
glioma (4 papers, 2013 to 2025). A benign or malignant brain and spinal cord tumor that arises from glial cells (astrocytes, oligodendrocytes, ependymal cells). "In this study, we found that spermine synthase (SMS) was highly expressed in gliomas that showed a poor clinical response to TMZ treatment." (PMID 41244832, 2025). "SMS mRNA expression, verified in glioma tissues and datasets, was higher in tumor than in non-tumor tissues and positively correlated with tumor grades." (PMID 40761256, 2025). "In our study, we found that SMS, a key enzyme in spermine production, was highly expressed in glioma patients who responded poorly to TMZ treatment." (PMID 41244832, 2025). "The expression levels of risk factors IL4I1, SMS, and ADI1 in high-grade gliomas were higher than those in lower‐grade gliomas, while the protein expression levels of protective factor GCLC, MSRB2, MTAP and MPST were exactly the opposite." (PMID 38057821, 2023). "Recently Nikhil et- al reports that SMS gene is one of the 55 survival genes that their suppression leads to glioma cell death." (PMID 23826488, 2013). "Among adverse prognostic regulators, SMS overexpression in gliomas was related to poor prognosis." (PMID 40761256, 2025). "Spermine synthase (SMS) was identified as a key PMRG in patients with gliomas." (PMID 40761256, 2025). "Analysis of TCGA data from glioma patients treated with TMZ revealed that the expression of spermine synthase (SMS) was significantly higher in patients with progressive disease (PD) compared to those with a complete response (CR), partial response (PR), or stable disease (SD)." (PMID 41244832, 2025). "Based on our analysis in human glioma tissues and the TCGA+CGGA dataset, SMS protein and mRNA expression were higher in tumor than in non-tumor tissues and positively correlated with tumor grades." (PMID 40761256, 2025).
hepatocellular carcinoma (4 papers, 2022 to 2023). A malignant tumor that arises from hepatocytes. "Transcriptome analysis revealed that in Huh7.5 hepatoma cells, the expression of polyamine biosynthesis genes (SRM, SMS, and AMD) was increased, while in hepatocyte-like HepaRG cells, the expression of the SAT1 gene involved in the degradation of spermine and spermidine was increased." (PMID 37189460, 2023).
neuroblastoma (4 papers, 2008 to 2025). Neuroblastoma (NB) is the most common solid, extracranial childhood tumor. "NB7M showed similar reductions in the ΔYm of SMS-KCNR, a chemotherapy-resistant neuroblastoma cancer cell line." (PMID 19002174, 2008).
pancreatic cancer (4 papers, 2022 to 2026). "The growth curve showed that over-expression of SMS can promote the growth of pancreatic cancer cells, while knockdown of SMS can inhibit their proliferation." (PMID 36276112, 2022). "Knockdown of METTL3 or IGF2BP3 significantly reduced the SMS protein expression and inhibited the migration of pancreatic cancer." (PMID 36276112, 2022). "Additionally, the results of transwell assays demonstrated that overexpression of SMS can promote the migration and invasion of pancreatic cancer cells, while knockdown of SMS had the opposite effect." (PMID 36276112, 2022). "Therefore, increased expression of SMS in pancreatic cancer cells promotes the proliferation, migration, and invasion of pancreatic cancer cells." (PMID 36276112, 2022). "In this study, we confirmed that overexpression of SMS can promote the increase of spermine levels in pancreatic cancer cells, knockdown of SMS can lead to increased spermidine, and the level of SMS protein is positively correlated with AKT phosphorylation and the PI3K-AKT/EMT pathways." (PMID 36276112, 2022). "Therefore, the highly expressed SMS protein in pancreatic cancer may be related to the expression of METTL3 and IGF2BP3, and the expression of METTL3 and IGF2BP3 related to the migration and invasion of pancreatic cancer." (PMID 36276112, 2022). "Therefore, it is worthwhile to examine the role of spermine synthase in pancreatic cancer." (PMID 36276112, 2022). "Additionally, we analyzed The Cancer Genome Atlas (TCGA) database and the results showed that the expression of SMS in cancer tissue specimens was significantly higher than that in adjacent tissues, and the expression of SMS was related to the prognosis of pancreatic cancer." (PMID 36276112, 2022). "We speculate that changes in the expression of SMS in pancreatic cancer could affect the levels of spermidine and spermine in cells, while changes in spermidine/spermine levels could affect the phosphorylation of AKT and ultimately affect the activation and inhibition of the AKT signaling pathway." (PMID 36276112, 2022). "Recent studies have also highlighted the role of ornithine aminotransferase (OAT1) and spermine synthase (SMS) in inducing tumor progression and migration in pancreatic cancer." (PMID 38547055, 2024). "As the stabilizers of m6A methylation, IGF2BP2 and IGF2BP3 can enhance the stability of B3GNT6 and spermine synthase (SMS) mRNA and protein expression, respectively, to promote the progression of pancreatic cancer." (PMID 36981005, 2023). "Spermine synthase (SMS) is an enzyme participating in polyamine synthesis; however, its function and role in pancreatic cancer remains elusive." (PMID 36276112, 2022). "Therefore, we speculate that METTL3 can regulate SMS mRNA m6A methylation and be recognized by IGF2BP3 to further affect the prognosis of pancreatic cancer." (PMID 36276112, 2022).
Obesity (3 papers, 2012 to 2023). Accumulation of substantial excess body fat. "An experimental study using knock-out of the enzyme involved in SM synthesis (SMS2) in mice supports a role of SMs in obesity." (PMID 36848351, 2023). "Obesity/T2D decreased expression of polyamine synthetic genes Odc (ornithine decarboxylase), Srm (spermidine synthase), and Sms (spermine synthase) that concomitantly resulted in a ~30% reduction in spermidine in the colon." (PMID 36714575, 2022).
osteoporosis (3 papers, 2018 to 2024). A condition of reduced bone mass, with decreased cortical thickness and a decrease in the number and size of the trabeculae of cancellous bone (but normal chemical composition), resulting in increased fracture incidence. "This is a whole field in itself, and the question is, ‘‘what is the nosologic description of these syndromes of osteoporosis in young adult women with heterozygous variants in PLS3 or MBTPS2 or SMS’’ in their reproductive years?’’." (PMID 38942908, 2024). "Female patients with expression of heterozygous genomic variants in X-Linked PLS3, MBTPS2 and SMS may have symptomatic osteoporosis." (PMID 38942908, 2024).
X-linked intellectual disability syndrome (3 papers, 2017 to 2024). "SRS (OMIM: 309583) is a rare X-linked intellectual disability syndrome associated with pathogenic variants in the SMS gene that lead to the loss or reduction of SMS enzymatic activity." (PMID 38463005, 2024).
autoimmune disease (2 papers, 2015 to 2020). A disorder resulting from loss of function or tissue destruction of an organ or multiple organs, arising from humoral or cellular immune responses of the individual to their own tissue constituents. "Another set of genes on the X chromosome that have bearing on autoimmune diseases are the spermine synthase (SMS) gene and the spermidine/spermine-N1-acetyltransferase (SAT1) gene at Xp22.1." (PMID 25763008, 2015). "Some other potential therapeutic targets for treating autoimmune diseases, such as SLE, are the polyamine synthesis (SMS, ODC, AMD1) and recycling (SAT1) enzymes, transglutaminases, peptidyl arginine deiminases (related to NETosis), and EBV genes." (PMID 34968240, 2020).
colon cancer (2 papers, 2022 to 2025). "Overexpression of SMS in liver, head and neck, and colon cancers has been associated with a poor prognosis; however, the underlying mechanism remains to be elucidated." (PMID 40761256, 2025). "At present, there are relatively few studies on SMS in tumors, although studies have shown that overexpression of SMS can promote the progression of colon cancer." (PMID 36276112, 2022).
Infertility (2 papers, 2019 to 2025). "The Gy deletion also extends upstream into the neighbouring spermine synthase (SmS) gene, which has been associated with hearing loss and infertility, thus confounding Gy mice as a model of XLH-related hearing loss." (PMID 30808384, 2019).